UBA1 (ubiquitin like modifier activating enzyme 1)
Diseases named in the same sentence as UBA1 in open-access papers (continued):
Sharing a sentence is not in itself a finding about the gene and the disease.
cancer (50 papers, 2012 to 2026). A tumor composed of atypical neoplastic, often pleomorphic cells that invade other tissues. "Analysis of male germline genomes across rare disease and cancer programmes identified 58 rare UBA1 variants in 92 participants; all variants were presented as hemizygous and presumed to be of germline origin and excluded from this study." (PMID 40415210, 2026). "Using comprehensive bioinformatics analyses, we identified the expression of UBA1, a gene frequently gained in cancer, as being associated with low levels of intratumoral CD8+ T cells, ICB resistance, and poor survival in ICB-treated cohorts." (PMID 39540840, 2025). "Here, we report that elevated expression of UBA1 is prevalent in cancer, associated with low levels of intratumoral CD8+ T cells, and predictive of immune checkpoint blockade (ICB) resistance and poor survival in ICB cohorts." (PMID 39540840, 2025). "Currently, the association between UBA1 mutations and cancer remains uncertain, yet there is a growing body of literature on the connection between non-M41 UBA1 mutations and various cancers." (PMID 39347709, 2024). "We also investigated the potential relationship between gene mutations in UBA1 and the prognosis of patients with different types of cancer." (PMID 39183260, 2024). "Among the eight identified E1 enzymes to date, the enzyme that initiates UBA1, aminoacylation and nadylation is the most characteristic enzyme and is associated with various aspects of cancer biology." (PMID 39183260, 2024). "Uba1 has been proposed as a target for treatment of cancers and other pathological states linked to detrimental levels of ubiquitin–proteasome activity and other ubiquitination-dependent activities (reviewed in31–33)." (PMID 31488855, 2019). "Finally, we analyzed the survival difference between UBA1/6 associated gene set SNV groups in the selected cancers, and found that only UBA1 had all statistical significance on OS, PFS, DFS and DFI in LIHC." (PMID 40046044, 2025). "Besides, we also found that only CD276 was positively associated with UBA1 in most cancers, however, there are many other immune checkpoints like CD44, CD86 and CD274 illustrating a positive correlation with UBA6." (PMID 40046044, 2025). "Survival analysis of the TCGA database showed a correlation between UBA1/6 gene expression and the prognosis of several cancers, indicating that higher UBA1 expression was associated with bad endpoint in tumor patients with LAML (p=0.021), LGG (p=0.019), LUAD (p=0.049), and LIHC (p=0.006)." (PMID 40046044, 2025). "We further investigated the prognostic risk of UBA1/6 in pan-cancer by COX analysis." (PMID 40046044, 2025). "Although research has identified the association between UBA1 expression and clinical parameters of specific cancer types, extending these findings to all cancer types may oversimplify the complex biological landscape of cancer." (PMID 39183260, 2024). "Previous studies have demonstrated a potential biological association between UBA1 and cancer." (PMID 39183260, 2024). "We used the cBioPortal database to study the mutation of UBA1 in pan‐cancer." (PMID 39183260, 2024). "Thus, it is possible that variants leading to partial loss of UBA1 function contribute to the development of cancers." (PMID 36823397, 2023). "By screening the NCATS drug library, containing 1978 compounds, we recently reported that TAK-243 (MLN7243), a first-in-class inhibitor of the ubiquitin-activating enzyme UBA1 (also known as UBE1) preferentially suppresses cell proliferation of SLFN11-deficient cancer cells." (PMID 35903760, 2022). "This may be particularly pertinent as gene mutations or alterations in UBA1 expression have been associated with cell proliferation and cancer." (PMID 27699224, 2016).
cancer (continued). "In order to investigate whether UBA1 can predict treatment response to cancer, data was obtained from ROCplotter to demonstrate the association between treatment outcomes and UBA1 expression for four types of cancer (BRCA, OV, GBM, and CRC)." (PMID 39183260, 2024). "However, the biological association mechanism of UBA1 in cancer is currently unclear." (PMID 39183260, 2024). "Intriguingly, significant enrichment of these pathways was observed in cancer cells with Uba1 depletion or TAK-243 treatment in vitro, particularly in the presence of IFN-γ stimulation." (PMID 39540840, 2025). "In agreement with this, we found that hypermethylation on the UBA1 promoter in cancer was rare, in contrast to the reported frequent hypermethylation on the MGMT promoter." (PMID 39540840, 2025). "Here, we summarized UBA1/6 SNV percentage in 33 cancer types by using the GSCA database, respectively." (PMID 40046044, 2025). "A positive correlation between the copy number of UBA1 and its mRNA expression implied that the UBA1 gene was accessible in chromatin in cancer." (PMID 39540840, 2025). "By screening candidate genes frequently gained in cancer, we identified expression of ubiquitin-like modifier-activating enzyme 1 (UBA1) as being the most negatively correlated with signatures related to effector CD8+ T cells." (PMID 39540840, 2025). "Intriguingly, apart from the T cell chemokines CXCL9 and CXCL10, we observed upregulation of surface MHC-I expression upon UBA1 inhibition or depletion in various cancer models." (PMID 39540840, 2025). "With a combined analysis (n = 115) of four publicly available RNA sequencing (RNA-seq) datasets from various cancer types, we found that high pretreatment expression of UBA1 was strongly predictive of ICB resistance (P = 0.009)." (PMID 39540840, 2025). "Based on our findings, clinical trials should be undertaken to evaluate UBA1 inhibitors (such as TAK-243) in combination with ICB as a new strategy to boost immunotherapy response across multiple cancer types." (PMID 39540840, 2025). "Functionally, UBA1 mediates cancer immune evasion, and importantly, inhibition of UBA1 by TAK-243 markedly suppresses tumor growth in combination with ICB, exhibiting the potential of tumor clearance." (PMID 39540840, 2025). "We performed a scale analysis of UBA1/6 expression in the TCGA database and found that they were highly expressed in most cancers." (PMID 40046044, 2025). "For different cancers, there were similarities and differences in the correlation between UBA1/6 expression and immune cells infiltrating the tumor." (PMID 40046044, 2025). "Concordantly, mRNA levels of UBA1 were upregulated in various cancer types compared with the adjacent normal tissues." (PMID 39540840, 2025). "UBA1 is a potential cancer biomarker and therapeutic target that mediates immune evasion through JAK1 degradation, and targeted UBA1 inhibition synergizes with immune checkpoint blockade to enhance antitumor immunity and survival." (PMID 39540840, 2025). "We further determined the prognostic value of UBA1 in ICB cohorts and found that high pretreatment UBA1 expression was strongly associated with poor survival in both individual cancer and pan-cancer cohorts." (PMID 39540840, 2025). "We found that in both individual cancer and pan-cancer cohorts, UBA1 expression was significantly negatively correlated with the expression of IFNG or CD8+ T-cell–related signatures." (PMID 39540840, 2025). "It was observed that the mRNA expression of UBA1 was significantly heightened in cancer tissues than in their paired paracancerous tissues, particularly among 16 tumor types, including BC." (PMID 39684409, 2024). "Our analysis indicates that UBA1 is closely related to the expression of chemokine receptors and chemokines in various cancers." (PMID 39183260, 2024). "The DNA methylation data and protein phosphorylation data from the UALCAN database further support the important role of UBA1 in pan‐cancer." (PMID 39183260, 2024).
cancer (continued). "It is indeed surprising that loss of function of UBA1 would lead to clonal advantage, as UPS has been the target of multiple anti-cancer drugs, and UBA1 itself was identified as cancer dependency in multiple studies." (PMID 39347709, 2024). "The relationship between UBA1 expression and the prognosis of cancer patients was estimated using clinical survival data from TCGA pan‐cancer." (PMID 39183260, 2024). "As shown in the heatmap, UBA1 is negatively correlated with chemokines, many receptors and immune stimulatory factors in pan‐cancer." (PMID 39183260, 2024). "In summary, our study not only comprehensively analysed the functional mechanisms and clinical value of UBA1 in pan‐cancer, but also validated for the first time the regulatory role of UBA1 in haematological tumours." (PMID 39183260, 2024). "UBA1 is closely related to immune checkpoint genes in most cancers, and in TGCT, UBA1 is significantly positively correlated with 8 immune checkpoint genes." (PMID 39183260, 2024). "We conducted a comprehensive analysis of the functional mechanism and role of UBA1 in pan‐cancer using multiple databases, including differential expression analysis, clinical pathological staging analysis, prognosis analysis and immune analysis." (PMID 39183260, 2024). "UBA1 inhibitors were originally developed for cancer treatment, based on the premise that cancer cells require more ubiquitylation compared to normal cells." (PMID 39347709, 2024). "Ubiquitin-Activating Enzyme E1 (UBA1), an E1 enzyme involved in the activation of ubiquitin enzymes, has been involved in the onset and progression of different cancers in humans." (PMID 39684409, 2024). "Variability in response to UBA1 inhibitors has been noted among cell lines even within the same cancer." (PMID 39347709, 2024). "It has been reported that UBA1 enzymes are more actively utilized in several cancer cells, and targeting UBA1 has shown promise as an effective anticancer strategy." (PMID 39684409, 2024). "Our pan‐cancer study comprehensively analysed the potential role of UBA1 in pan‐cancer immune regulation and predictive immunotherapy." (PMID 39183260, 2024). "In order to investigate the immunological role of UBA1 in cancer environments, the estimated values of UBA1 in pan‐cancer were calculated." (PMID 39183260, 2024). "In summary, this study reveals the important role of UBA1 in pan‐cancer and validates its regulatory role in haematological tumours, providing new ideas and theoretical basis for the value of UBA1 in tumour treatment." (PMID 39183260, 2024). "Subsequent OS, PFS, DFS and DSS analyses also showed that the expression of UBA1 is closely related to the clinical prognosis of various cancers, especially LAML and LGG." (PMID 39183260, 2024). "The histogram shows a significant correlation (p < 0.01) between UBA1 and the immune subtypes of 10 types of cancer and we present the top three cancer types." (PMID 39183260, 2024). "In order to investigate the relationship between the expression of UBA1 and clinical pathological features in various cancers, we evaluated the expression of UBA1 in stages I, II, III and IV of cancer patients." (PMID 39183260, 2024). "UBA1 is positively and significantly correlated with matrix score, ImmuneScore and microenvironment score in many cancers." (PMID 39183260, 2024). "Analysing the top 100 co‐expressed genes of UBA1 in pan‐cancer on GEPIA2.0, the top 5 genes (CDK16, ELK1, KDM5C, RBM10 and TBC1D25) were highly correlated with UBA1 in most cancer types." (PMID 39183260, 2024). "In this study, we systematically analysed the expression patterns, immune mechanisms and pathological differences of UBA1 in pan‐cancer." (PMID 39183260, 2024). "UBA1, the most important E1 enzyme in humans, is responsible for initiating many dysregulated downstream effects in malignant tumors, making it as an attractive target in anticancer strategies." (PMID 36959858, 2023).
cancer (continued). "Lastly, our Uba6/Ub-AMP structures, and in particular, differences with the human Uba1 active site, will provide a framework for drug discovery efforts targeting specifically this enzyme for therapeutic intervention in cancer and other diseases." (PMID 35986001, 2022). "To simplify the analysis and look for statistical significance, we compared levels of UBA1 expression with NEDD8 to determine if there was a correlation both in the pan-cancer dataset as well as specific tumor types." (PMID 34685640, 2021). "In contrast to the development of UBA1 inhibitors for the treatment of cancer, upregulation of UBA1 levels and/or activity is likely to be required for the treatment of neurodegeneration." (PMID 26432019, 2015). "Specifically, we could find that UBA1/6 appeared to be consistently negatively correlated with all cancers in these scores." (PMID 40046044, 2025). "UBA1 and UBA6 are highly expressed in most cancer types, which may be associated with poor prognosis of patients." (PMID 40046044, 2025). "Importantly, in these cancer types, UBA1 also exhibited positive correlations between DNA and mRNA levels." (PMID 39540840, 2025). "In line with this, Uba1 depletion only modestly affected cancer cell proliferation in vitro." (PMID 39540840, 2025). "Importantly, surface expression of MHC-I in cancer cells was significantly increased after Uba1 depletion or inhibition, both in vitro with IFN-γ stimulation and in vivo." (PMID 39540840, 2025). "Whether UBA1 functions in cancer immune evasion and whether UBA1 inhibition improves the efficacy of immunotherapies via eliciting antitumor immunity remain unexplored." (PMID 39540840, 2025). "Since aberrant protein ubiquitylation is typically found in the cancer cell and the E1-activating step is almost exclusively catalysed by UBA1, novel small molecule compounds are continuously developed against this protein, further expanding future therapeutic possibilities." (PMID 39773572, 2025). "In pan-cancer, the total expression level of UBA1 was higher than that of UBA6." (PMID 40046044, 2025). "UBA1 expression was significantly correlated with MSI in 11 types of cancer (p < 0.05)." (PMID 39183260, 2024). "UBA1 expression was significantly correlated with TMB in 10 types of cancer (p < 0.05)." (PMID 39183260, 2024). "Our analysis results show that LUAD, LUSC, PAAD and LIHC had higher phosphorylation degree in S46 site of UBA1 protein, revealing that protein phosphorylation of UBA1 at S46 site might serve as a facilitator in the development and progression of these cancers." (PMID 39183260, 2024). "Subsequently, we investigated whether UBA1 is differentially expressed in different cancer immune subtypes through the TISIDB database." (PMID 39183260, 2024). "In addition, in many cancers, UBA1 is positively correlated with matrix score, immune score and microenvironment score." (PMID 39183260, 2024). "In summary, our study conducted a comprehensive investigation into the UBA1 mRNA expression characteristics, its prognostic value, and its relationship with tumour‐infiltrating immune cells across various cancers, utilizing a multi‐omic bioinformatics approach." (PMID 39183260, 2024). "Through the analysis of mRNA sequencing data of BC patients, the mRNA expression of UBA1 was observed to be notably enhanced in cancer tissues relative to controls, and high UBA1 expression was linked to worse overall survival (OS), disease-specific survival (DSS), and progress-free survival (PFS)." (PMID 39684409, 2024). "The results of survival analysis showed that the expression of UBA1 may be related to the prognosis of cancer." (PMID 37417208, 2023). "Previous studies indicated that UBA1 is an essential upstream enzyme for ubiquitination-dependent signaling of both DSBs and replication stress in human cells, which was of great significance in the maintenance of genome integrity and cancer treatment." (PMID 36959858, 2023).
cancer (continued). "We propose that Myr and some of its analoguesreported in this study may be promising candidates for developingeffective Uba1 inhibitors for cancer treatment." (PMID 37636942, 2023). "In a genome-wide study to identify genes which are important for cancer survival through RNAi screening, UBA1 and UBA2 (encoding SAE active subunit) genes have been identified to be essential for survival after knockdown in large pan-cancer RNA interference screens in cancer cell lines." (PMID 33805973, 2021). "Studies of these inhibitors supported that UBA1 might be an attractive target for drug discovery to fight against cancer, neurodegenerative disorders, and infectious diseases." (PMID 32258175, 2020). "Inhibitors of UBA1 represent an effective target spot for cancer therapy." (PMID 33046974, 2020). "Uba1 is required for the initial activation of ubiquitin for almost all ubiquitination events, with a consequently wide range of biological effects in normal and pathological states such as cancers and neurodegenerative diseases (reviewed in31–33)." (PMID 31488855, 2019). "In addition, co-expression analysis using TCGA database could reveal the correlation between UBA1/6 expression and immune checkpoints in pan-cancer." (PMID 40046044, 2025). "Finally, we analyzed the association between UBA1 and UBA6, and found that they were positively related with most cancers, especially PRAD and GBM, which indicated that they may modulate each other in the ubiquitination system to make it more sophisticated." (PMID 40046044, 2025). "Whether and how UBA1 functions in cancer progression or cancer immune evasion remains unaddressed." (PMID 39540840, 2025). "Therefore, UBA1 may play an important role in haematological tumours (DLBCL and AML), which are one of the leading causes of cancer death worldwide." (PMID 39183260, 2024). "Therefore, it is necessary to study the relationship between TMB and UBA1 in cancer." (PMID 39183260, 2024). "However, the pathological mechanism of UBA1 in pan‐cancer is not fully understood." (PMID 39183260, 2024). "A cell-permeable inhibitor for the E1 enzyme UBA1 is developed and used in clinical trials, but given the pleiotropic behavior of E1 enzymes, these inhibitors could only be used in acute settings such as aggressive cancers." (PMID 36926679, 2023). "Furthermore, UBA1 is also a key component of the UPS, since it catalyzes the first step in ubiquitin conjugation to mark cellular proteins for degradation via the proteasome and has been implicated in the development of cancer and neurodegenerative diseases." (PMID 35518205, 2022). "Ubiquitin-like modifier activating enzyme 1 (UBA1), a key enzyme in the ubiquitin-proteasome pathway, has been reported to play a role in the pathogenesis of various malignant tumors." (PMID 42038032, 2026). "Our study reveals UBA1 as a predictive biomarker for clinical outcomes in ICB cohorts, mediating cancer immune evasion and ICB resistance." (PMID 39540840, 2025). "Our findings indicate that the differential expression of UBA1 and UBA6 is significantly correlated with patient survival rates, tumor grade, and cancer stage." (PMID 40046044, 2025). "Moreover, the high expression of UBA1 had poor prognosis in most tumours, which may be related to its involvement in various cancer‐related pathways such as cell cycle, as well as its methylation level, protein phosphorylation level, immune cell infiltration and immune therapy response." (PMID 39183260, 2024). "Therefore, UBA1 may play a crucial role in the occurrence, development, and immunity of cancer." (PMID 39183260, 2024). "TAK-243 is a small molecular inhibitor of the proteins UBA1, UBA6 and NAE, used for cancer treatment in pre-clinical animal models." (PMID 36293188, 2022). "The profile of expression of UBA1, UBE2C, UBE2T, UBE2O, and CCNF in BRCA seemed to support their involvement in cancer initiation and progression." (PMID 34201347, 2021).